S100A12 (S100 calcium binding protein A12)
Diseases named in the same sentence as S100A12 in open-access papers (continued):
Sharing a sentence is not in itself a finding about the gene and the disease.
COVID-19 (continued). "Genes involved in neutrophil degranulation and/or other neutrophil functions had increased expression levels in patients with severe manifestations of COVID-19, such as S100A8/9 and S100A12, encoding calprotectin and calgranulin, respectively, as recently reported." (PMID 34135895, 2021). "Finally, using RNA-Seq data from five independent studies on COVID-19 infection, I demonstrated that S100A12 was indeed a valuable prognostic marker for COVID-19 severity." (PMID 34108608, 2021). "Thus, S100A12 is a valuable novel prognostic marker for COVID-19 severity and deserves more attention." (PMID 34108608, 2021). "These insights suggest S100 proteins could serve as biomarkers for disease severity, prognosis, and therapeutic response; for instance, high levels of S100A8/A9 may indicate severe COVID-19 or pulmonary fibrosis, and S100A12 and S100A8/A9 can help monitor graft rejection in lung transplant patients." (PMID 41164170, 2025). "The blocking of S100A12 from binding to TLR4 may inhibit the downstream pro-inflammatory signal and is therefore of potential value for designing effective therapeutics against COVID-19-associated acute necrotizing encephalopathy." (PMID 37848421, 2023). "Therefore, S100A12 activation was a marker for severe and critical COVID-19." (PMID 36649304, 2023). "Additionally, since most of the S100A12 activation is accompanied by IFI27 activation in patients with severe COVID-19, it is unlikely that the inability of ISG activation is to blame for most of the severe symptoms, which has implications in the usage of interferon as a therapeutic option." (PMID 36649304, 2023). "This showed that S100A12 activation may last for a long time in certain COVID-19 patients." (PMID 36649304, 2023). "Finally, we demonstrated that influenza virus infection also induces the expression of S100A7, S100A8, S100A9, and S100A12 in the alveolus chip, a finding that is consistent with recent clinical observations from COVID-19 patients that exhibit late stage lung infections with SARS-CoV-2 virus." (PMID 35396513, 2022). "Thus, S100A12 expression is elevated in a subgroup of hospitalized COVID-19 patients." (PMID 34108608, 2021). "Notably, we observed that the classical monocytes and myeloid cells from severe COVID-19 patients in the single-cell RNA-seq data expressed high levels of S100A12, the gene encoding EN-RAGE, but not the typical inflammatory molecules IL-6 and TNF-α." (PMID 32788292, 2020). "Based on the Degree, MCC, Closeness, Betweenness, and MNC algorithms of the CytoHubba plug-in, six genes (FPR1, FCGR2A, TLR4, S100A12, CXCL1, and LTF) were confirmed as hub genes related to COVID-19 severe." (PMID 38674681, 2024). "Of the 52 well-described IPF signature genes in our study, only 7 were upregulated in COVID-19 patients with NP, whereas in the SP group, only few genes, namely PLBD1, S100A12, and MCEMP1, were upregulated." (PMID 39205185, 2024). "A serum concentration of 0.88 μg/mL S100A12 indicates VRE with an 80% sensitivity and a 68% specificity in patients with severe COVID-19." (PMID 39066246, 2024). "We performed a study using peripheral blood mRNA-seq data from 41 COVID-19 patients to obtain the immune-characterized genes of COVID-19 severe disease, namely, the hub genes (FPR1, FCGR2A, TLR4, S100A12, CXCL1, and LTF)." (PMID 38674681, 2024). "A concentration of 0.88 μg/mL S100A12 exhibited an 80% sensitivity and a 68% specificity for the diagnosis of VRE superinfection in patients with severe COVID-19." (PMID 39066246, 2024). "Patients with severe COVID-19 and vancomycin-resistant enterococcus (VRE) infection had increased S100A12 levels." (PMID 39066246, 2024). "In this study, a two-tiered innate immune response was demonstrated in COVID-19 patients, and a two-gene marker (IFI27/S100A12) for this two-tiered innate immune response was proposed." (PMID 36649304, 2023).
COVID-19 (continued). "Overall, the stepwise increase of S100A12 activation and fast waning of IFI27 activation were consistently observed in whole blood and PBMC of patients with COVID-19." (PMID 36649304, 2023). "Overall, S100A12 activation was correlated with disease severity (with or without COVID-19), while IFI27 activation was more specific to COVID-19." (PMID 36649304, 2023). "Comparative analyses between rheumatoid arthritis and COVID-19 samples revealed similar pro-inflammatory disease patterns regulated via SPP1 and S100A12, leading to activation of proinflammatory CD14+ monocytes and PD-L1+ neutrophils." (PMID 35681519, 2022). "S1 cells exhibited the highest expressions of alarmins S100A8, S100A9, S100A12 and toll-like receptors TLR4 and TLR8, all of which are involved in neutrophil activation and were the most mature neutrophils in both KD and Severe COVID-19 patients." (PMID 36159873, 2022). "Meanwhile, CXCL8, S100A8, S100A9, S100A12, FCGR1A, PADI4, and BCL2A1 showed significant increases in severe COVID-19 when compared with mild COVID-19 (p <0.05)." (PMID 36159873, 2022). "We investigated the persistence of increased plasma SPP1, S100A12, GAS6, and PROS1 into the SARS-CoV-2– post–COVID-19 phase, often characterized by complex pathologies." (PMID 34143756, 2021). "Of prognostic importance for COVID-19 patients, higher levels of SPP1 and S100A12 at the time of hospital admission and before antiinflammatory treatment were predictive of urgency for subsequent Intensive Care Unit (ICU) transfer." (PMID 34143756, 2021). "EN-RAGE was also found to be a marker of inflammation in severe sepsis in the analysis of scRNA-seq data, and S100A12 was highly expressed by classical monocytes and myeloid cells from COVID-19 severe patients." (PMID 38674681, 2024). "In this study, we used mRNA-seq data from the peripheral blood of COVID-19 patients to identify six COVID-19 severe immune characteristic genes (FPR1, FCGR2A, TLR4, S100A12, CXCL1, and L TF), and found neutrophils to be the critical immune cells in COVID-19 severe disease." (PMID 38674681, 2024). "In the moderate COVID-19 group, serum S100A12 levels did not correlate with age (r = −0.197, p = 0.125) or BMI (r = −0.110, p = 0.547) and were similar between sexes (p = 0.258)." (PMID 39066246, 2024). "Serum S100A12 did not correlate with BMI and age of controls and COVID-19 patients and did not significantly differ between sexes." (PMID 39066246, 2024). "In patients with severe COVID-19 serum S100A12 of non-survivors and survivors was comparable (p = 0.185)." (PMID 39066246, 2024). "The 6 patients with moderate disease and the 7 patients with severe COVID-19 needing dialysis had similar serum S100A12 levels compared to patients with no need for dialysis." (PMID 39066246, 2024). "Serum S100A12 had an area under the receiver operating characteristic curve (AUROC) for predicting severe compared to moderate COVID-19 of 0.643 (p = 0.006), indicating that it is not an excellent marker for assessing disease severity." (PMID 39066246, 2024). "In the patient cohort with severe COVID-19, the 27 patients with bacterial bloodstream infections had similar serum S100A12 levels compared to non-infected patients (p = 0.136)." (PMID 39066246, 2024). "In the cohort with moderate COVID-19, six patients were infected with bacteria, but serum S100A12 of infected and non-infected patients was similar (p = 0.100)." (PMID 39066246, 2024). "The 21 severe COVID-19 patients with fungal superinfection had serum S100A12 comparable to those in the patients without fungal infection (p = 0.871)." (PMID 39066246, 2024). "In this dataset, S100A12 expression was significantly higher in hospitalized COVID-19 patients compared to non-hospitalized patients (p = 0.000386)." (PMID 36649304, 2023). "This clearly demonstrated a step-wise increase of S100A12 activation in the COVID-19 patients with increasing severity (p-value not calculated due to small sample size)." (PMID 36649304, 2023).
COVID-19 (continued). "In this dataset, S100A12 expression was similarly distributed in both groups (p = 0.402) with median values of 9.28 and 9.22 in the patient groups with and without COVID-19, respectively." (PMID 36649304, 2023). "The combined observations from these two datasets (GSE161731 and GSE157103) showed the stepwise increase of S100A12 activation in COVID-19 patients from non-hospitalized patients to hospitalized patients, and from hospitalized non-ICU patients to ICU patients." (PMID 36649304, 2023). "In this dataset, S100A12 expression was significantly higher in the ICU group with COVID-19 compared to the non-ICU group (p = 7.815e-07)." (PMID 36649304, 2023). "In comparison, for patients without COVID-19, S100A12 expression was above 12.2 in one of the 10 non-ICU patients, and 12 of the 16 ICU patients (75%), while IFI27 expression was above 6.0 in none of the 10 non-ICU patients, and only 2 of the 16 ICU patients." (PMID 36649304, 2023). "It showed that activation of S100A12 was much more pronounced in critical COVID-19 patients than that of non-critical counterparts." (PMID 36649304, 2023). "Moreover, in TNF-α activated monocytes, ITF3756 reduces the expression of additional biomarkers of severe COVID-19, such as PTX3, ICAM-1, S100A12, PD-L1 and MMP9, further supporting a potential role for this molecule in the treatment of the disease." (PMID 35592335, 2022). "COVID-19 patients with severe respiratory distress were characterized by an aberrant raised SPP1 and S100A12 cytokine signature that could predict the urgency for ICU transfer and persisted into the post–COVID-19 phase after hospital discharge." (PMID 34143756, 2021). "Next, we investigated whether concomitant pharmacological drug treatment, demographic factors (age and sex), and COVID-19 comorbidities contributed to the plasma levels of SPP1, S100A12, GAS6, and PROS1." (PMID 34143756, 2021). "It was evident that S100A12 expression was significantly elevated in the hospitalized COVID-19 group compared to the non-hospitalized COVID-19 group (p = 0.00039)." (PMID 34108608, 2021). "S100A12 and PROS1 were unrelated to age in COVID-19 and in SARS-CoV-2– pneumonia." (PMID 34143756, 2021). "Moreover, a much larger proportion of these neutrophils was in a hyperactivated state in COVID-19 patients, marked by upregulated IL1B, CXCL8 and S100A12 expression." (PMID 34226537, 2021). "Furthermore, blood levels of IL1α, calprotectin (a heterodimer made of S100A8 and S100A9), S100A12, S100B and HGBM1 appear to correlate with COVID-19 severity." (PMID 34293006, 2021). "Vasopressor therapy of 41 patients with severe COVID-19 was not related to higher S100A12 levels." (PMID 39066246, 2024). "Serum S100A12 did not correlate with the viral load in patients with moderate (r = 0.117, p = 0.392) and severe (r = 0.076, p = 0.607) COVID-19 and also did not correlate with antibody titer in moderate (r = 0.188, p = 0.603) and severe (r = 0.046, p = 0.752) disease." (PMID 39066246, 2024). "In addition to these three markers, the ICU group tend to be separated from non-ICU patients by OSM and S100A12, whereas all COVID-19 patients can be distinguished from healthy controls by CASP8, IFNγ, IL-18R and CCL8." (PMID 33239683, 2020). "S100A12 has shown very low expression in mild COVID-19 patients and no expression in severe COVID-19 patients, particularly when subgrouping differences across CD8 memory T cells and ɣδ T cells, meaning it could be a representative target in viral-induced diseases." (PMID 38892107, 2024). "Overall, S100A12 activation was rarely observed in non-hospitalized patients with COVID-19, while it could be observed in a significant portion of hospitalized patients with COVID-19, depending on the distribution of severity." (PMID 36649304, 2023).
COVID-19 (continued). "However, although reduced, the levels of SPP1 and S100A12 remained significantly higher than in healthy control donors, irrespective of whether the prior disease trajectory of COVID-19 was mild/moderate or severe." (PMID 34143756, 2021). "In module 2, mono-CD14+ cells in patients with severe COVID-19 exhibited higher expression levels of glycolysis-related genes (LDHA and PKM) and PPP-related genes (PGD and TKT), which may be involved in the proinflammatory response (upregulation of S100A8, S100A9, S100A12, and IL1B)." (PMID 33936072, 2021). "Serum S100A12 did not correlate with CRP, procalcitonin and interleukin-6 levels in the serum of patients with moderate and severe COVID-19." (PMID 39066246, 2024). "Overall, this clearly demonstrated a stepwise increase of S100A12 activation in COVID-19, while IFI27 activation was similarly predominant in hospitalized COVID-19 patients irrespective of disease severity." (PMID 36649304, 2023). "However, it increased expression levels of alarmins S100A12 and S100A9, and it decreased the expression of MHCII and ENTPD1 of CD14+ monocytes, suggesting that persistent levels of SPP1 may contribute to long–COVID-19 pathologies by skewing monocytes toward a proinflammatory phenotype." (PMID 34143756, 2021). "Stratification of patients by symptoms showed that SPP1 and S100A12 levels remained increased and GAS6 decreased in convalescent COVID-19 patients, irrespective of symptom category." (PMID 34143756, 2021).
Sepsis (49 papers, 2010 to 2026). Sepsis is defined as life-threatening organ dysfunction caused by a dysregulated host response to infection. "CONCLUSIONS: Higher plasma S100A12 levels were independently associated with the development of sepsis-associated acute kidney injury in critically ill patients with sepsis." (PMID 41572197, 2026). "To assess the diagnostic value of S100A12 for sepsis-associated myocardial dysfunction, we performed ROC curve evaluation." (PMID 40926894, 2025). "In conclusion, sepsis patients show increased peripheral neutrophils, an RF model based on 4 neutrophil-associated genes demonstrates strong diagnostic ability, and S100A12 serves as a key biomarker for sepsis." (PMID 41305822, 2025). "We developed S100A12-related PPI networks in sepsis and AF, identifying S100A12 and its associated proteins and analyzing their expression levels." (PMID 39444551, 2024). "In our research, bioinformatics analysis helped us to identify sepsis as an independent risk factor for new-onset AF and to pinpoint S100A12 as a potential susceptibility gene." (PMID 39444551, 2024). "Early amlexanox administration can reduced S100A12 expression, dampened inflammation, and lessened new-onset AF risk in sepsis." (PMID 39444551, 2024). "Our model highlights the substantial upregulation of the S100A12 gene, which encodes the small protein Calgranulin C in patients with sepsis and is more pronounced in patients with septic shock." (PMID 38892107, 2024). "Compared to the control group, S100A12 expression was markedly higher in the sepsis group (P < 0.001), demonstrating significant diagnostic value for sepsis with an AUC of 0.997 (95% CI: 0.997–1.000, P < 0.001)." (PMID 39444551, 2024). "S100A12 was identified as a core interaction gene with elevated levels in sepsis and AF, underscoring its diagnostic and predictive significance." (PMID 39444551, 2024). "Infants with confirmed LOS also had up-regulated expression of S100A12, which encodes for the S100A12 alarmin previously implicated during neonatal and adult sepsis." (PMID 32479514, 2020). "Therefore, this study aims to investigate the diagnostic value of S100A12 in sepsis-induced myocardial dysfunction." (PMID 40926894, 2025). "Existing studies have linked S100A12 levels to mortality of sepsis and organ dysfunction in sepsis." (PMID 40926894, 2025). "Nevertheless, through bioinformatics analysis, this study has identified key genes and pathways in sepsis and established S100A12 as an independent risk factor for prognosis in sepsis, highlighting its critical role in sepsis progression and providing new insights into targeted interventions." (PMID 41305822, 2025). "Our findings also linked S100A12 serum expression in acute sepsis mice with HR, suggesting that its increased expression may significantly reduce HR." (PMID 39444551, 2024). "Notably, there was an inverse correlation between S100A12 expression and HR, and administration of amlexanox effectively reduced the risk of developing new-onset AF in sepsis." (PMID 39444551, 2024). "Furthermore, bioinformatics analysis and experimental evidence concerning sepsis and AF identified S100A12 as a potential pathological target for new-onset AF in sepsis, strongly linked to the inflammatory response." (PMID 39444551, 2024). "Hence, S100A12 offers significant clinical diagnostic value in sepsis and AF, emphasizing its importance in diagnosing, predicting, and prognosticating new-onset AF in sepsis." (PMID 39444551, 2024). "This study demonstrated that early amlexanox administration in acute sepsis mice could lessen inflammatory response and S100A12 expression, lowering AF risk and suggesting its efficacy in preventing and treating new-onset AF in sepsis." (PMID 39444551, 2024). "It is unclear whether S100A12 significantly influences the immune system, which may be associated with sepsis-related mortality." (PMID 35723375, 2022).